NCKAP5L (NCK associated protein 5 like)
Description:
Regulates microtubule organization and stabilization. Promotes microtubule growth and bundling formation and stabilizes microtubules by increasing intense acetylation of microtubules. Both tubulin-binding and homodimer formation are required for NCKAP5L-mediated microtubule bundle formation.
Synonyms: Cep169; KIAA1602; FP1193
Tractability: PROTAC: ubiquitination databases record sites on it; its protein half-life has been measured.
Gene: Protein-coding gene on chromosome 12 (49,791,140 to 49,828,750, reverse strand). Ensembl gene ENSG00000167566.
Subcellular location: Cytoplasm, cytoskeleton, microtubule organizing center, centrosome
Gene Ontology:
Molecular function: protein binding
Biological process: microtubule bundle formation; microtubule depolymerization
Cellular component: centrosome; microtubule plus-end
Genetic constraint (gnomAD): Loss-of-function variants: 54 observed, 87.29 expected, observed/expected ratio (o/e) 0.62, 90% interval 0.5 to 0.78. The upper end of that interval is the gene's LOEUF score, 0.78, which puts it in group 3 of 6, group 1 being the genes least tolerant of losing a copy. Missense variants: 1,733 observed, 1,596.5 expected, observed/expected ratio (o/e) 1.09, 90% interval 1.04 to 1.13. Synonymous variants: 762 observed, 672.46 expected, observed/expected ratio (o/e) 1.13, 90% interval 1.07 to 1.2.
Homologues: Orthologues: chimpanzee NCKAP5L (99% identical), macaque NCKAP5L (98% identical), dog NCKAP5L (90% identical), pig NCKAP5L (90% identical), guinea pig NCKAP5L (87% identical), mouse Nckap5l (87% identical), rabbit NCKAP5L (86% identical), rat Nckap5l (85% identical), tropical clawed frog nckap5l (36% identical), zebrafish nckap5l (30% identical), Drosophila melanogaster CG42663 (8% identical). Paralogues in human: NCKAP5 (20% identical).
Diseases named in the same sentence as NCKAP5L in open-access papers:
NCKAP5L is named in the same sentence as 6 diseases in open-access papers, as found by Europe PMC text mining. Sharing a sentence is not in itself a finding about the gene and the disease. The quoted sentences say what the papers report.
Obesity (2 papers, 2013 to 2023). Accumulation of substantial excess body fat. "TMBIM4 is located within ±1 Mb of the SNP rs1531343 conferring susceptibility to T2DM, while NCKAP5L, TOMM5, and BAP1 are mapped within ±1 Mb of SNPs conferring susceptibility to obesity." (PMID 24455749, 2013). "Using the same method, seven highly ranked genes (BAP1, GRB14, HSP90AB1, ITGA5, NCKAP5L, SP1, and TOMM5) within ±1 Mb of obesity SNPs were identified." (PMID 24455749, 2013). "Eight genes (BCAT1, BMP2 K, CSRNP2, MYNN, NCKAP5L, SAP30BP, SLC35B4, and SP1) were isolated as candidates for obesity." (PMID 24455749, 2013). "The rest of the candidates, C2orf15, DENND1B, MRPL30, POC1B, RP4-655J12.3, TMBIM4, BMP2 K, CSRNP2, NCKAP5L, TOMM5, and BAP1, may be novel genes related to T2DM or obesity." (PMID 24455749, 2013).
atherosclerosis (1 paper, 2022). A disease characterized by the build-up of fatty material and calcium deposition in the arterial wall resulting in partial or complete occlusion of the arterial lumen. "Endou, Hdac7, Senp1, Olfr286, Olfr285, Nckap5l, Smarcd1, Lima1, Fam186a, and Espl1 are probable candidate genes for distal Chr15 atherosclerosis QTL (Ath53)." (PMID 36078077, 2022).
NCKAP5L also shares sentences with these, for which no sentence is quoted: autism (1 paper); bipolar disorder (1); cancer (1); schizophrenia (1).